ANGPTL4 (angiopoietin like 4)
Diseases named in the same sentence as ANGPTL4 in open-access papers (continued):
Sharing a sentence is not in itself a finding about the gene and the disease.
cancer (continued). "Interestingly, halofuginone was also able to inhibit the ability of TGF-β to stimulate ANGPTL4 and CXCR4 expression, two factors identified as key players to prime cancer cells for metastasis respectively towards the lungs and towards the bones or the lungs." (PMID 26015407, 2015). "Previous studies have indicated a negative role for ANGPTL4 in other cancer types, and ANGPTL4 has previously been shown to be activated by HIF-1α and to confer protection against hypoxia-induced apoptosis in cell lines." (PMID 26205780, 2015). "ANGPTL4 is a novel secretory glycoprotein which has been reported to interact with specific extracellular matrix (ECM) proteins and integrins to facilitate cell migration during wound healing and cancer development." (PMID 23925665, 2013). "Moreover, through disruption of endothelial cell–cell junctions by inducing angiopoietin-like 4 (Angptl4) expression, TGF-β has been shown to increase the permeability of blood vessels and stimulate the trans-endothelial movement of cancer cells." (PMID 22111550, 2012). "Further analysis suggested that modulation of angiogenesis-related genes (including ANGPTL4, FN1, HSPG2, SRPX2, KLK5, L1CAM, Prr22, FOXJ1, IL24, and TRIM54) potentially contributes to anlotinib resistance, as anlotinib is a multi-targeted anti-angiogenesis drug for cancer therapy." (PMID 31572680, 2019). "Doing a differential expression between the two clusters of cancer fibroblasts, we found metastatic fibroblasts were found to express higher levels of soluble factors compared to primary fibroblasts including, CXCL12, S100A6, S100A10, SFRP2,SFRP4,IGF1, CXCL14, ANGPTL4 and IL6." (PMID 30383866, 2018). "Expression of ANGPTL4 in the cancerous liver tissue was positively correlated with expression of XPO4 (CC=0.506, P<0.001) in carcinoma liver tissue, expression of elF5A2 (CC=0.469, P<0.001) in carcinoma liver tissue and expression of elF5A2 (CC=0.245, P<0.001) in paracancerous liver tissue." (PMID 23251252, 2013). "Whereas the ANGPTL4 N-terminal domain was mainly involved in the endocrine regulatory role of lipid metabolism, insulin sensitivity, and glucose homeostasis, the COOH-terminal fibrinogen-like domain may be a key regulator of the complex signaling during cancer development." (PMID 29389861, 2018). "A general trend of negative correlation between B cell (20/33 cancers), naïve CD8 T cell (11/33), Neutrophil (10/33), and central memory B cell (9/33) immune infiltration and ANGPTL4 expression was evident." (PMID 40233044, 2025). "Accumulating evidence has shown that the expression of CCAL is substantially higher in cancer than in non-cancerous tissues and that CCAL promotes angiogenesis and metastasis through escalating, for example, FOXM1 and angiopoietin-like 4 (ANGPTL4) expression." (PMID 35055115, 2022).
cardiovascular disease (34 papers, 2016 to 2026). "ANGPTL4 participates in the modulation of lipid metabolism and angiogenesis in a variety of tissues and has been observed to play a role in cardiovascular diseases, with abnormal lipid metabolism as a risk factor." (PMID 41169876, 2025). "Pathologically, ANGPTL4 has been implicated in many disorders, such as metabolic and cardiovascular diseases, inflammation, and cancers." (PMID 34773076, 2021). "Furthermore, to understand the clinical implications of our studies, we measured circulating levels of ANGPTL4 in patients with cardiovascular disease to determine the association of ANGPTL4 with clinical outcomes." (PMID 36782020, 2023). "Several studies have suggested that ANGPTL4 is associated with increased risk factors for cardiovascular disease and might act as a potential therapeutic target against cardiovascular diseases." (PMID 34422410, 2021). "Additionally, several Dox_H3K27ac-upregulated genes including Egr-1, Adam17, Dusp6, Ddit4 and Angptl4 might potentially contribute to Dox-induced cardiotoxicity, since they have been proved to be associated with the progression of cardiovascular disease." (PMID 39014511, 2024). "As a regulator of lipoprotein lipase, ANGPTL4 modulation impacts lipid homeostasis, thus rendering it a promising therapeutic target for cardiovascular disorders." (PMID 40006981, 2025). "Aryal and colleagues (2019) reviewed the role of ANGPTL4 in cardiovascular disease and highlighted accumulating evidence showing the direct association between ANGPTL4 and systemic atherosclerosis." (PMID 39728292, 2024). "For example, there is strong genetic evidence implicating both lipoprotein lipase (LPL) and angiopoietin-like protein 4 (ANGPTL4) as therapeutic targets for lipid-lowering and cardiovascular disease reduction." (PMID 39407214, 2024). "One research group reported that serum ANGPTL-4 concentrations potentially predict future cardiovascular disorders in patients with AF." (PMID 37051105, 2023). "ANGPTL4 has surfaced as a principal regulator of plasma lipid metabolism by functioning as a potent inhibitor of lipoprotein lipase in cardiovascular disease." (PMID 35285130, 2022). "Recent large-scale human genetic studies and animal models have collectively established the central role of ANGPTL4 in the regulation of TG levels and cardiovascular diseases." (PMID 34646996, 2021). "We identified one known locus (ANGPTL4) and four new loci (PLCL1, RC3H2, TMPRSS5, and LDLRAD1) associated with cardiovascular disease risk that warrant further investigation." (PMID 33186364, 2020). "This study identified one known locus (ANGPTL4) and four new loci (PLCL1, RC3H2, TMPRSS5, and LDLRAD1) associated with cardiovascular disease risk that warrant further investigation." (PMID 33186364, 2020). "Angptl4 plays a role in the regulation of TG homeostasis and lipid metabolism by suppressing lipoprotein lipase (LPL) activity, and common non-coding variants in LPL gene loci and TGs levels are associated with cardiovascular diseases." (PMID 40296165, 2025). "In addition, the roles of ANGPTL4 in glucose and lipid metabolism were recently established in cardiovascular disease." (PMID 34680556, 2021). "Our findings corroborate the literature regarding the important roles of ANGPTL4, ANGPTL3, and endostatin in cardiovascular diseases." (PMID 39728292, 2024). "This indicated that ANGPTL3, ANGPTL4, and ANGPTL8 play important role in cardiovascular disease through regulation of lipid metabolism." (PMID 32440963, 2020). "Thus, the ‘biological distance’ between ANGPTL3 and cardiovascular disease may be greater than for LPL and ANGPTL4, suggesting that statistical power may also be lower, even if the relative efficacy of these drug targets might be similar in clinical practice." (PMID 39407214, 2024).
metabolic disorders (27 papers, 2013 to 2025). "This work establishes a chronological paradigm of cholesterol sensing and identifies GFPT1 and ANGPTL4 as key regulators bridging glycosylation and lipid pathways, providing mechanistic insights into cholesterol-associated metabolic disorders." (PMID 40806239, 2025). "Past studies have shown Angptl4 to be a potential metabolic regulator that is linked to several metabolic diseases." (PMID 39630889, 2024). "Research has shown the role of ANGPTL4 in the development of metabolic disorders based on observation of humans with loss-of-function mutations." (PMID 36144281, 2022). "Conversely, enhanced ANGPTL4 expression in various mouse models consistently causes increased blood TGs and facilitates the development of metabolic disorders." (PMID 34646996, 2021). "ANGPTL4 may be a promising target for therapeutic inhibition for reduction of metabolic disease risk in humans." (PMID 29899519, 2018). "Targeting these specific receptor interactions can modulate the various physiological and pathological effects of ANGPTL4, providing new treatment strategies for fibrosis, vascular diseases, and metabolic disorders." (PMID 39840089, 2024). "But recent studies indicated that Angptl4 has a role in various metabolic as well as non-metabolic disorders and is particularly important in several energy homoeostasis aspects." (PMID 35321016, 2022). "Taken together, exercise-induced ANGPTL4 plays a role in regulating lipid metabolism in metabolic diseases." (PMID 33498410, 2021). "Recent studies have indicated that plasma ANGPTL4 also regulates the clinical relevance of metabolic diseases and is positively correlated with the plasma levels of FFA." (PMID 33498410, 2021). "Our data, in combination with findings of favorable lipid profiles and reduced risk of coronary artery disease, provide human genetics support for ANGPTL4 inhibition as a therapeutic strategy for prevention and possibly treatment of metabolic disease." (PMID 29899519, 2018). "Further studies are warranted to provide additional evidence to support the targeting of ANGPTL4 in the treatment of metabolic disorders." (PMID 29502266, 2018). "Recent studies on ANGPTL4 have emphasized the need to consider its role in metabolic diseases." (PMID 33498410, 2021). "Indeed, some studies have reported that ANGPTL4 plays an anti‐inflammatory role in metabolic diseases." (PMID 32638512, 2020). "Matrix protein molecules such as Adipoq, Angptl4, Col4a4, Hrg, Tgfbi, Tgm2, Vcan and Vtn increase with age, and they may promote the occurrence of fatty liver during aging by affecting fat accumulation and metabolic disorders." (PMID 40537154, 2025). "Furthermore, ANGPTL4 was reported to be involved in metabolic diseases." (PMID 36553482, 2022). "Omental fat from obese individuals with higher ANGPTL4 displayed signs of inflammation and meta-inflammation, i.e., apoptosis, cell stress, and matrix rearrangement markers, known to be involved in the alteration of insulin sensitivity and development of metabolic diseases." (PMID 33003532, 2020). "ANGPTL4, a member of the angiopoietin family, plays complex roles in lipid metabolism by inhibiting LPL, which affects diabetes and metabolic disorders." (PMID 40743234, 2025). "Induction of ANGPTL4 inhibits LPL activity and increases circulating triglycerides concentration; hence, this protein exerts an influence on the development of metabolic disorders." (PMID 36144281, 2022). "The evidence on ANGPTL4-mediated blood lipid regulation comes from animal studies, while data on the relationship between ANGPTL4 and LPL expression in AT and metabolic diseases in humans are very limited." (PMID 33003532, 2020). "The purposes of our study were to evaluate variations of serum ANGPTL4 and FGF21 concentrations in periparturient dairy cows and changes in these serum analyte concentrations of energy-related metabolic disorders in early lactation dairy cows." (PMID 30103741, 2018).
metabolic disorders (continued). "Angiopoietin-like protein 4 (ANGPTL4), primarily secreted by CAFs, is a multifunctional protein belonging to the angiopoietin family that plays key roles in various metabolic and non-metabolic diseases." (PMID 41154598, 2025). "Unfortunately, global depletion of ANGPTL4 results in severe metabolic abnormalities, inflammation, and fibrosis when mice are fed a high-fat diet (HFD), limiting our understanding of the contribution of ANGPTL4 in metabolic disorders." (PMID 29563332, 2018). "Although ANGPTL4 modulates LPL activity and is important in fine-tuning lipid metabolism in response to physical activity, further studies are required to verify whether exercise-induced ANGPTL4 secretion mediates the benefits of exercise for metabolic diseases." (PMID 33498410, 2021). "Indeed, we demonstrated the existence of an independent relationship between VDR and ANGPTL4 expression in human VAT, regardless of potential confounders such as age, sex, body adiposity, and metabolic disease." (PMID 33003532, 2020).
infection (24 papers, 2009 to 2026). The state of being infected such as from the introduction of a foreign agent such as serum, vaccine, antigenic substance or organism. "Despite the evidence from animal studies, the role of ANGPTL4 in human infections associated with vascular leakage remains relatively unexplored." (PMID 40006981, 2025). "Infected ANGPTL4+/+ mice treated with anti-cANGPTL4 MAb were protected against infection-associated lung damage, with better lung tissue integrity and reduced edema compared to infected but untreated ANGPTL4+/+ mice, thus confirming the findings of the ANGPTL4 knockout experiments." (PMID 31164474, 2019). "By using ELISA, we found that the infection-caused upregulation of VEGFA, PDGFB, and ANGPTL4 in the brains of Egr-1−/− mice significantly decreased compared with that in WT mice." (PMID 38233877, 2024). "The Egr-1−/− mice were used to evaluate the contribution of Egr-1 to VEGFA, PDGFB, and ANGPTL4 production in response to the infection." (PMID 38233877, 2024). "Then, we showed that H. pylori-infected AGS cells increased ANGPTL4 gene and ANGPTL4 protein expressions in infection dose-dependent as well as time-dependent manners." (PMID 39022746, 2024). "Then, we also confirmed that H. pylori infection induced human primary GECs as well as mouse primary GECs to increase ANGPTL4/Angptl4 expression and ANGPTL4 production, both of which were dependent of cagA and in infection dose- and time-dependent manners." (PMID 39022746, 2024). "At the same time, we determined ANGPTL-3 and ANGPTL-4 gene expression in mRNA samples isolated from sixteen day-long infections of permissive hepatoma cells with HCV-3a." (PMID 34360721, 2021). "Compared to mock-infected cells, ANGPTL-3 was down-regulated almost by half in early infection, while ANGPTL-4 remained unchanged." (PMID 34360721, 2021). "The downregulation of HIF-1α expression by ROS savenger and HIF-1α inhibitor or knockdown by lentiviral shRNA infection diminished NiCl2-activated ANGPTL4 expression." (PMID 31963541, 2020). "In vitro, after the challenge of meningitic E. coli strain, we observed a significant and time-dependent increase of ANGPTL4 in hBMECs, with a sharp increase emerging at 2 hours post infection (hpi)." (PMID 31766605, 2019). "Via immunofluorescence (IF) assay, we demonstrated that the expression of ANGPTL4 protein was significantly increased in mouse brains along with the infection of meningitic E. coli." (PMID 31766605, 2019). "ANGPTL4−/− mice with secondary Flu+S3 and Flu+19F infections exhibited less pulmonary edema than their ANGPTL4+/+ counterparts." (PMID 31164474, 2019). "The fact that angiopoietin is known to limit the formation of actin stress fibres correlates well with our findings that at 48 h post infection transcription of ANGPTL4 further increased and transcription of gamma actin (ACTG1 and ACTG2) declined." (PMID 23326599, 2013). "The ChIP-seq data revealed the significant Egr-1-binding peaks in the promoter region of VEGFA (chromosome 6 position 43,771,366 − 43,771,763), PDGFB (chromosome 22 position 39,243,987 − 39,244,220), and ANGPTL4 (chromosome 19 position 8,363,766-8,364,203) in the infection group." (PMID 38233877, 2024). "In our case of H. pylori infection, we identify a novel ANGPTL4 regulating cytokine, IL-17A, which exerts synergistic effects on the induction of ANGPTL4 by activating the NF-κB signaling pathway, where its pathway is similar to other pathogen infection." (PMID 39022746, 2024). "Therefore, ANGPTL4 can serve as a potential biomarker to assess the severity of CAP based on host response after infection." (PMID 37821811, 2023). "Inflammation and infection have been shown to increase serum ANGPTL4 levels." (PMID 32695883, 2020).
infection (continued). "We demonstrated preliminarily that meningitic E. coli induced the expression of ANGPTL4 through the activation of PPARβ/δ signaling pathway, and ANGPTL4 contributed to the infection-mediated BBB disruption via the ARHGAP5/RhoA/MYL5 signaling cascade, affecting the actin cytoskeleton." (PMID 31766605, 2019). "ANGPTL4 was canonically regulated via the PPAR-associated pathways, and we next investigated the possible involvement of PPAR transcriptional factors in hBMECs upon the infection." (PMID 31766605, 2019). "Indeed, infection of primary hepatocytes with ANGPTL4 adenovirus significantly decreased secretion of glucose into the medium, suggesting that ANGPTL4 may lower plasma glucose by decreasing hepatic glucose output." (PMID 30944669, 2019). "To further explore the impact of the FGF19/ANGPTL4 axis on CRCLM, we knocked down FGF15 in CT26‐luc cells (shFGF15) using lentiviral infection before injecting these cells into the portal vein of the mice to establish a CRCLM mouse model." (PMID 39716892, 2025). "Our data suggest systemic changes in the host during early infection, indicated by the altered expression of PRs, DDX5, BCL2, ANGPTL4, and other regulatory genes during early MDV infection." (PMID 39066292, 2024). "The 17 DEGs upregulated after infection with huH1N1 were shared with the swH1N1 infection (DDX58 (RIG-I), RSAD2 (Viperin), MX2, MX1, OAS1, ANGPTL4, IRF7, ISG15, IFIT1, ISG12(A), DDX60, BST2, IFI44, XAF1, LGALS3BP, RTP4, and IFI6)." (PMID 39247193, 2024). "Angptl4, which contributes to the anti-inflammatory response and Myh15, were downregulated in 5-ASKH infection." (PMID 36190414, 2022). "In mice, Angptl4 gene expression was also detected in wild-type (WT) H. pylori-infected mice, but not in ΔcagA-infected mice, reaching a peak 12 weeks post-infection (p.i.), together suggesting an important role of cagA in increasing ANGPTL4 in vivo." (PMID 39022746, 2024). "We verified the PPARs pathway-mediated generation of ANGPTL4 in BMECs in response to meningitic E. coli challenge and demonstrated for the first time that ANGPTL4-triggered ARHGAP5/RhoA/MYL5 signaling cascade contributed to the BBB disruption by the infection." (PMID 31766605, 2019). "Then, compared to the human primary gastric mucosa either not infected or infected with ΔcagA, the expressions of ANGPTL4 gene and ANGPTL4 protein were significantly increased in/from those infected with WT H. pylori in infection dose-dependent as well as time-dependent manners ex vivo." (PMID 39022746, 2024). "Furthermore, high VRL was a significant predictor for ANGPTL-3 and ANGPTL-4 levels after treatment, but not during infection, as would have been expected." (PMID 34360721, 2021). "In this study, E. tenella infection led to intestinal mucosal damage and caecal bleeding; the ANGPTL4 gene and the ACSL5 gene can promote cell development and angiogenesis, and they were both significantly upregulated in the PPAR pathway on the seventh day after chicken infection with coccidioides." (PMID 31159150, 2019). "We further tested their contributions in the induction of ANGPTL4 by using their specific inhibitors and showed that the PPARβ/δ inhibitor GSK3787 as well as PPARγ inhibitor T0070907 could significantly attenuate the infection-induced upregulation of ANGPTL4." (PMID 31766605, 2019).
retinopathy (6 papers, 2021 to 2025). "Intravitreous injection of AAV‐shANGPTL4 in the DR model, we found that knocking down ANGPTL4 in the retina of diabetic rats can significantly improve the degree of retinopathy and improve the apoptosis of retinal cells." (PMID 40032635, 2025). "The results of the analysis were verified, and it was further demonstrated that ANGPTL4 could improve the expression level of ligand‐receptor while reducing retinopathy." (PMID 40032635, 2025). "Since these factors are also increased in DR patients and implicated in the pathogenesis of retinopathy, the reduced retinal pathogenesis observed upon TRAP1 inhibition might be associated with decreases in the levels of these factors, as well as those of VEGF, ANGPTL4, and ANG2." (PMID 37983591, 2024).
bacterial infection (2 papers, 2019 to 2023). "Effects of anti-cANGPTL4 antibody treatment in secondary bacterial infections were also confirmed using ANGPTL4−/− mice." (PMID 31164474, 2019).